TF (transferrin)
Diseases named in the same sentence as TF in open-access papers (continued):
Sharing a sentence is not in itself a finding about the gene and the disease.
Leigh syndrome (1 paper, 2023). A progressive neurological disease defined by specific neuropathological features associating brainstem and basal ganglia lesions. "This work may have broader implications in the development of diagnostic markers for Leigh Syndrome, in which serum iron, transferrin saturation, serum ferritin, or serum hepcidin can be readily analyzed clinically." (PMID 36799301, 2023).
leiomyosarcoma (1 paper, 2023). An uncommon, aggressive malignant smooth muscle neoplasm, usually occurring in post-menopausal women. "It was also revealed that miR-93 and miR-106b also regulate TF expression in leiomyosarcoma cells through binding to the 3'UTR of TF mRNA." (PMID 37280670, 2023).
lipodystrophy (1 paper, 2025). A congenital or acquired disorder characterized by abnormal loss or redistribution of the adipose tissue in the body. "BMI and AOM distance were positively correlated with TF-SMA (r = .633, P < .001 and r = .545, P < .001, respectively) and TF-RR (r = .581, P < .001 and r = .490, P < .001, respectively) distances in patients with lipodystrophy." (PMID 39352627, 2025). "Leptin levels were positively correlated with TF-SMA and TF-RR distances in patients with lipodystrophy (r = .717, P < .001 and r = .721, P < .001, respectively)." (PMID 39352627, 2025).
liver cysts (1 paper, 2021). "An inverse association of the liver cysts’ size with BMI, transferrin, protein serum levels, percental liver fat (PDFF), as well as uric acid levels, was found." (PMID 34083637, 2021).
macular edema (1 paper, 2024). "Contrary to our finding, a cohort study of NPDR patients indicated that patients with macular edema had significantly higher ferritin levels, and significantly lower serum iron and transferrin saturation levels than controls." (PMID 39519580, 2024).
male infertility (1 paper, 2013). The inability of the male to effect fertilization of an ovum after a specified period of unprotected intercourse. "Transferrin is one of the serum proteins that has been characterized in the seminal plasma, but its role in male infertility is unclear." (PMID 23663294, 2013).
metastatic prostate carcinoma (1 paper, 2016). A carcinoma that arises from the prostate gland and has spread to other anatomic sites. "This may be the main reason for the downregulation of the AP1 TF in metastatic prostate cancer." (PMID 28005952, 2016).
Miscarriage (1 paper, 2019). A pregnancy that ends at a stage in which the fetus is incapable of surviving on its own, defined as the spontaneous loss of a fetus before the 22th week of pregnancy. "Networking analyses suggest cross talk between the four dysregulated proteins, that is, HP, TF, ApoA1, and TTR as a connecting link between miscarriage history and MeS." (PMID 30783564, 2019). "Increased expression of TF, HP protein (three isoforms), SYNE 1, serpin 38, and ApoA1 in groups A, C, and D provides a better insights into the molecular link between the history of miscarriage and MeS." (PMID 30783564, 2019). "A cross talk between HP, ApoA1, TF, and TTR estabishs link between miscarriage and MeS." (PMID 30783564, 2019).
mitochondrial dysfunction (1 paper, 2016). "Our results demonstrated that HFe rats had increased plasma non-transferrin bound iron (NTBI), malondialdehyde (MDA), cardiac iron and MDA levels and cardiac mitochondrial dysfunction, leading to LV dysfunction." (PMID 27428732, 2016).
mucinous tumors (1 paper, 2019). "Similarly, apolipoprotein A1 has been detected in conjunction with transthyretin and transferrin in low grade mucinous tumors." (PMID 31315664, 2019).
muscle degeneration (1 paper, 2019). "Studies have shown increased serum ferritin levels, transferrin saturation coefficient, and decreased transferrin in ALS patients, which could reflect a general increase in iron stores or be a consequence of on-going muscle degeneration." (PMID 30949015, 2019).
muscular atrophy (1 paper, 2023). The loss of muscle tissue due to inactivity or disease. "Other studies have reported the role of transferrin in regulating neural regeneration or muscular atrophy." (PMID 36771359, 2023).
muscular dystrophy (1 paper, 2023). Muscular dystrophy (MD) refers to a group of more than 30 genetic diseases characterized by progressive weakness and degeneration of the skeletal muscles that control movement. "In this study, either monoclonal antibodies or fragment antibodies targeting transferrin are conjugated to the oligonucleotides (oral presentations from Dyne Therapeutics and Avidity BioScience at the annual Parent Project Muscular Dystrophy conference, June 2022)." (PMID 36269327, 2023).
myasthenia gravis (1 paper, 2024). Myasthenia gravis (MG) is a rare, clinically heterogeneous, autoimmune disorder of the neuromuscular junction characterized by fatigable weakness of voluntary muscles. "Transferrin is also used to treat autoimmune diseases such as myasthenia gravis (MG)." (PMID 39125124, 2024).
Mycoplasma infection (1 paper, 2017). "Elimination of Mycoplasma infection restored the levels of ALB, TF, and CYP3A4 genes as well as proteins to normal levels." (PMID 29075618, 2017).
myeloid leukemia (1 paper, 2023). A clonal proliferation of myeloid cells and their precursors in the bone marrow, peripheral blood, and spleen. "Evidence supporting this includes an enrichment of TF and signaling gene mutations within BMP-like T-ALL blasts (a mutational spectrum shared with myeloid leukemias), non-T lineage marker expression, and shared drug sensitivity profiles with myeloid leukemia stem cells." (PMID 37961674, 2023).
myeloid malignancies (1 paper, 2024). "Finally, CUX149, a TF frequently mutated in myeloid malignancies and whose knockdown leads to an MDS-like phenotype, presented similar activity in non-del(5q) cells, showing higher activity than at diagnosis." (PMID 38902243, 2024).
myositis (1 paper, 2023). "[68Ga]Ga-apo-transferrin also showed capability of S. aureus infection in a murine myositis model." (PMID 37388440, 2023).
narcolepsy (1 paper, 2020). A sleep disorder characterized by a tendency for excessive sleepiness during the day which occurs even after adequate sleep in the nighttime. "Even for the less heritable MCV, the top significant gene sets included hematological categories such as “Transferrin”, “Erythrocyte Indices”, “Hematocrit”, “Narcolepsy”, and “Iron”—all of which have verified and clinically relevant connections to trait." (PMID 32542026, 2020).
nematode infection (1 paper, 2016). "Previously, comparative transcriptome analysis revealed that, for ramie, drought stress and root lesion nematode infection regulated 24 TF genes (containing three NACs, two MYBs, and one EFR) and 40 TFs genes (containing 10 bHLHs, five MYBs, two NACs, and one ERF), respectively." (PMID 27034936, 2016).
nephritis (1 paper, 2024). Inflammation of renal tissue. "Additionally, there were increased urinary levels of transferrin, α1‐MG, IgG, β2‐microglobulin, and microalbumin, confirming the successful establishment of a nephritis mouse model." (PMID 39394911, 2024).
normal pressure hydrocephalus (1 paper, 2018). A form of compensated hydrocephalus characterized clinically by a slowly progressive gait disorder (see gait disorders, neurologic), progressive intellectual decline, and urinary incontinence. "The N-glycan proteoform of CSF transferrin is a potential biomarker for normal pressure hydrocephalus (iNPH)." (PMID 30220890, 2018).
ocular hypertension (1 paper, 2022). Abnormally high intraocular pressure. "Herein, we assessed the protective effects of TF on RGC survival, using ex vivo rat retinal explants exposed to iron, NMDA-induced excitotoxicity, or CoCl2-induced hypoxia, and an in vivo rat model of ocular hypertension (OHT)." (PMID 36361544, 2022).
ocular infection (1 paper, 2015). "In a hyperendemic setting, 208 1–6 year-old children from a single village in Kongwa District, TZ, had a TF prevalence of 47% and ocular infection rates of 24% (previously published in3, 6)." (PMID 26687891, 2015). "For the hypoendemic setting, TF was present in 2·9% and ocular infection in 1·8% of 680 1–9 year-olds evaluated." (PMID 26687891, 2015).
ovarian clear cell cancer (1 paper, 2025). An invasive malignant neoplasm that arises from the ovary and is characterized by a predominance of clear and hobnail malignant epithelial cells. "In ovarian clear cell carcinoma, high TF expression increases VTE risk via thrombin generation." (PMID 40361374, 2025).
pancreatic adenocarcinoma (1 paper, 2022).
papillary thyroid carcinomas (1 paper, 2024). "KS chains have also been detected on transferrin and thyroglobulin in papillary thyroid carcinoma where the KS chains are of diagnostic value." (PMID 38376199, 2024).
paratyphoid A fever (1 paper, 2011). "We examined the assay characteristics of TUBEX TF and several prototypic TUBEX tests (TUBEX PA, TUBEX 12T, TUBEX 12P, TUBEX 12TP [including the variant, TUBEX 12TPP]) in the detection of typhoid and paratyphoid A fever." (PMID 21935450, 2011).
peritonitis (1 paper, 2020). Inflammation of the peritoneum (tissue that lines the abdominal wall and covers most of the organs in the abdomen). "Upon using radioactive iron-labeled transferrin, peritoneal transferrin was found as a potential direct iron source for the growth of bacteria causing peritonitis." (PMID 32752018, 2020).
placental abruption (1 paper, 2021). Vaginal bleeding preceding the 20th week of gestation. "It is noteworthy that the increase in FVII concentration is the highest among the plasma coagulation factors in pregnancy at term, which allows for a fast and efficient response to the high amount of TF following placental abruption, resulting in rapid local clot formation." (PMID 34895336, 2021). "Pregnancy increases the inactive form substantially; thus, a huge quantity of FVII is ready to bind to the tissue factor expressed locally in large amounts after placental abruption, and the TF-FVIIa complex is subsequently launches extrinsic coagulation pathway." (PMID 34895336, 2021).
pneumococcal infection (1 paper, 2018). Infections with bacteria of the species streptococcus pneumoniae. "As the anemic individuals are more prone to pneumococcal diseases, the serum transferrin must have a role to determine the host survival against pneumococcal infection." (PMID 30246592, 2018).
pneumococcal meningitis (1 paper, 2008). An acute purulent infection of the meninges and subarachnoid space caused by Streptococcus pneumoniae, most prevalent in children and adults over the age of 60. "The poor prognosis seen in patients with pneumococcal meningitis complicated by HUS is consistent with the earlier observation that the severity of pneumococcal meningitis is related to neuraminidase activity and TF exposure in the central nervous system." (PMID 17564729, 2008).
pneumonic plague (1 paper, 2020). A plague in which the bacteria have infected the lungs. "Yersiniabactin promoted the progression of bubonic and pneumonic plague, by scavenging iron directly from transferrin and lactoferrin." (PMID 33537016, 2020).
podoconiosis (1 paper, 2024). A disease of the lymphatic vessels of the lower extremities that is caused by chronic exposure to irritant soils. "On the other hand, the most likely causes of the observed low hemoglobin in podoconiosis patients might be related to the release of inflammatory proteins like hepcidin and lactoferrins which have high affinity to iron than transferrin and result in low serum iron and inhibit iron absorption." (PMID 39689160, 2024).
polycystic kidney disease (1 paper, 2017). A usually autosomal dominant and less frequently autosomal recessive genetic disorder characterized by the presence of numerous cysts in the kidneys leading to end-stage renal failure. "In MDRD study, six factors independently predicted a faster decline in GFR: greater urine protein excretion, polycystic kidney disease (PKD), lower serum transferrin, higher mean arterial pressure, black race, and lower serum HDL cholesterol." (PMID 28380035, 2017).
proctitis (1 paper, 2025). An inflammatory process affecting the anus. "A set of biomarkers (pro-hepcidin, IL-6, TNF, hemoglobin, ferritin, transferrin) and genetic polymorphisms were linked to proctitis." (PMID 40506902, 2025).
prostate intraepithelial neoplasia (1 paper, 2022). A neoplastic proliferation of the epithelial cells that line the acini and the ducts of the prostate gland. "As well as driving the formation of prostate intraepithelial neoplasia, overexpression of TF MYC could further suppress target gene HSH2D." (PMID 35164166, 2022).
prostate tumors (1 paper, 2010). "Furthermore, prostate tumors express this TF and its expression increases in relapsed hormone refractory tumors." (PMID 20500816, 2010).
Protein-losing enteropathy (1 paper, 2016). Abnormal loss of protein from the digestive tract related to excessive leakage of plasma proteins into the lumen of the gastrointestinal tract. "Protein losing enteropathy was suspected due to the combination of low albumin and reduced serum levels of IgA, IgG, IgM, and transferrin combined with gastrointestinal symptoms." (PMID 27891267, 2016).
pulmonary alveolar proteinosis (1 paper, 2019). A rare lung disorder characterized by the filling of the pulmonary alveoli with proteinaceous material which stains positive with periodic acid-Schiff stain. "Similarly, patients with pulmonary alveolar proteinosis (PAP), a disease defined by severe accumulation of surfactant in the airspaces and hypoxemia, also present higher concentrations of iron, ferritin, transferrin, and lactoferrin in the bronchoalveolar lavage." (PMID 30609678, 2019).
pulmonary embolism (1 paper, 2019). The obstruction of the pulmonary artery or one of its branches by an embolus, sometimes associated with infarction of the lung. "Systemic administration of cells with increased TF expression may present a safety concern, such as pulmonary embolism." (PMID 31096722, 2019).
pulpitis (1 paper, 2021). Inflammation of the dental pulp. "A transcription factor- (TF-) DEmRNA network was built to identify the critical TFs involved in pulpitis." (PMID 33777260, 2021). "Several transcription factors have been identified to be involved in the TF-gene regulatory network of pulpitis, including GATA2, ETS1, FOXP3, STAT1, FOS, and JUN." (PMID 33777260, 2021).
rectal tumors (1 paper, 2021). "MAZ is a hypoxia tolerance induction TF, which would be required substantially in the colon and rectal tumors." (PMID 34934770, 2021).
Respiratory tract infection (1 paper, 2025). An infection of the upper or lower respiratory tract. "Furthermore, patients suffering from severe respiratory tract infections demonstrated high levels of TF expression, strongly indicating that this upregulation may contribute to the pathogenesis of thrombosis." (PMID 40821797, 2025).
retinal diseases (1 paper, 2020). "We summarize evidence of the potential therapeutic effect of iron chelation in retinal diseases and especially the interest of transferrin, a ubiquitous endogenous iron-binding protein, having the ability to treat or delay degenerative retinal diseases." (PMID 32183063, 2020).
retinoblastoma (1 paper, 2023). A malignant tumor that originates in the nuclear layer of the retina. "These polymer nanoparticles (PMNP-VCR-FA-TF) were designed in a way to be capable of delivering a significant dose of VCR chemotherapeutic drug to Y79 retinoblastoma cancer cells based on key advantages including an average size of 80 nm and the use of two ligands, i.e., folic acid and transferrin." (PMID 38102193, 2023).
rhabdomyosarcoma (1 paper, 2020). A rare aggressive malignant mesenchymal neoplasm arising from skeletal muscle. "Our data reveal a hijacked enhancer network that disrupts the stepwise CR TF logic of normal skeletal muscle development (PAX3 to MYOD to MYOG), replacing it with an “infinite loop” enhancer logic that locks rhabdomyosarcoma in an undifferentiated stage." (PMID 32416589, 2020).
Salmonella Infections (1 paper, 2023). Infections with bacteria of the genus SALMONELLA. "The protein–protein interaction (PPI) and protein-TF interaction network by STRINGDB analysis suggests that FOXO3 is a hub gene in the network and is closely related to Salmonella infection along with NF-κB1." (PMID 37098463, 2023). "The protein–protein interaction (PPI) and protein -TF interaction networks by STRINGDB analysis suggests that FOXO3 was hub gene in the network and closely related in Salmonella infection with NF-κB1." (PMID 37098463, 2023).
scoliosis (1 paper, 2022). A congenital or acquired spinal deformity characterized by lateral curvature of the spine. "This study showed that BL/TBV ≥15%, combined with pulmonary comorbidities, pre‐transferrin < 200 mg/dL, and nonidiopathic scoliosis were independent risk factors for the development of PRCs following PSDS in EOS population." (PMID 35686538, 2022). "BL/TBV ≥15%, combined with pulmonary comorbidities, pre‐transferrin < 200 mg/dL, and nonidiopathic scoliosis play an important role for the development of PRCs in this population." (PMID 35686538, 2022).
Shaheen syndrome (1 paper, 2022). "Transferrin glycosylation analyses showed a type 2 pattern in agreement with defective Golgi trafficking in COG6‐CDG except in Shaheen syndrome." (PMID 35068072, 2022).
skin aging (1 paper, 2021). The gradual irreversible changes in structure of skin that occur as a result of the passage of time.. "TF ETS1, which was regulated through the signaling pathway activated by ligand NGF, has been identified to be associate with skin aging." (PMID 34073305, 2021). "The TF E2F7 was also regulated by protein AIFM1 to downregulate target gene APAF1 in both young-adult and middle-aged skin aging." (PMID 34073305, 2021). "TF AR downregulated not only target gene TYR through triggering TF MITF to promote melanin synthesis, but also target gene CDH1, which was modified by phosphorylation, to promote cell-cycle, apoptosis and DNA damage in both middle-aged and elderly skin aging." (PMID 34073305, 2021). "As TF FOXM1, which was modified by phosphorylation, was activated, the target gene CAT was upregulated to inhibit ROS accumulation in both young-adult and middle-aged skin aging." (PMID 34073305, 2021).
Sotos syndrome (1 paper, 2025). Sotos syndrome is a rare multisystemic genetic disorder characterized by a typical facial appearance, overgrowth of the body in early life with macrocephaly, and mild to severe intellectual disability. "In comparison, the Sotos-only cohort (n = 8) showed significant enrichment in CORUM (n = 95) and TF (n = 133), whereas the overlapping group (exon 3 deletion and Sotos syndrome) revealed associations with CORUM (n = 19) and HPA (n = 5)." (PMID 41153407, 2025).
streptococcal infection (1 paper, 2007). Any of the several infectious disorders caused by members of streptococcus, a genus of gram positive bacteria belonging to the family Streptococcaceae. "Since TF expression is under the control of transcription factors such as nuclear factor κB (NFκB), which is also activated by TLR2, it is tempting to speculate that tlr2 polymorphisms may influence the severity of coagulation disorders in invasive streptococcal infections." (PMID 17660410, 2007).